KRTAP4-1 (keratin associated protein 4-1)
Description:
In the hair cortex, hair keratin intermediate filaments are embedded in an interfilamentous matrix, consisting of hair keratin-associated proteins (KRTAP), which are essential for the formation of a rigid and resistant hair shaft through their extensive disulfide bond cross-linking with abundant cysteine residues of hair keratins. The matrix proteins include the high-sulfur and high-glycine-tyrosine keratins.
Synonyms: KAP4.10; KRTAP4-10; KRTAP4.10; KAP4.1
Tractability: No criterion of Open Targets' tractability assessment is met for any kind of drug.
Gene: Protein-coding gene on chromosome 17 (41,184,100 to 41,184,911, reverse strand). Ensembl gene ENSG00000198443.
Pathways (Reactome):
Developmental Biology: Keratinization
Gene Ontology:
Molecular function: protein binding
Cellular component: cytosol; keratin filament
Genetic constraint (gnomAD): Loss-of-function variants: 1 observed, 0.36 expected, observed/expected ratio (o/e) 2.78. That is too few expected variants to judge how well the gene tolerates losing a copy. Missense variants: 155 observed, 180.21 expected, observed/expected ratio (o/e) 0.86, 90% interval 0.75 to 0.98. Synonymous variants: 52 observed, 57.32 expected, observed/expected ratio (o/e) 0.91, 90% interval 0.73 to 1.14.
Homologues: Orthologues: chimpanzee KRTAP4-1 (98% identical), rat Krtap4-3 (82% identical), mouse Krtap4-16 (82% identical), macaque KRTAP4-1 (77% identical), mouse Krtap5-24 (46% identical), mouse Krtap5-2 (40% identical), mouse Krtap5-26 (40% identical), rat Krtap5-8 (40% identical), rat AABR07006049.1 (38% identical), mouse Krtap5-20 (37% identical). Paralogues in human: KRTAP4-12 (71% identical), KRTAP4-11 (67% identical), KRTAP4-6 (67% identical), KRTAP4-3 (66% identical), KRTAP4-9 (66% identical), KRTAP4-5 (64% identical), KRTAP4-8 (62% identical), KRTAP4-7 (62% identical), KRTAP4-4 (60% identical), KRTAP4-2 (58% identical), KRTAP10-7 (47% identical), KRTAP10-11 (46% identical), and 35 more.